IDH1 (isocitrate dehydrogenase (NADP(+)) 1)
Description:
Catalyzes the NADP(+)-dependent oxidative decarboxylation of isocitrate (D-threo-isocitrate) to 2-ketoglutarate (2-oxoglutarate), which is required by other enzymes such as the phytanoyl-CoA dioxygenase. Plays a critical role in the generation of NADPH, an important cofactor in many biosynthesis pathways. May act as a corneal epithelial crystallin and may be involved in maintaining corneal epithelial transparency (By similarity).
Synonyms: IDH; PICD; HEL-216; HEL-S-26; IDCD; IDP; IDPC
Tractability: Small molecule: an approved drug acts on it; a structure with a bound ligand is known; a high-quality ligand is known; it has a high-quality binding pocket. Antibody: its Gene Ontology location is reachable by antibodies, with high confidence. PROTAC: ubiquitination databases record sites on it; its protein half-life has been measured; a small molecule that binds it is known.
Target class: Enzyme; Oxidoreductase
Chemical probes: AGI-5198 (high quality), GSK864 (high quality), ML309
Gene: Protein-coding gene on chromosome 2 (208,236,224 to 208,266,095, reverse strand). Ensembl gene ENSG00000138413.
Subcellular location: Cytoplasm, cytosol; Peroxisome
Subcellular location (Human Protein Atlas): Cytosol; Nuclear bodies
Pathways (Reactome):
Cellular responses to stimuli: NFE2L2 regulating TCA cycle genes
Disease: Abnormal conversion of 2-oxoglutarate to 2-hydroxyglutarate
Immune System: Neutrophil degranulation
Metabolism: NADPH regeneration
Protein localization: Peroxisomal protein import
Gene Ontology:
Molecular function: cadherin binding; identical protein binding; isocitrate dehydrogenase (NADP+) activity; magnesium ion binding; protein binding; protein homodimerization activity; NAD binding; NADP binding; oxidoreductase activity, acting on the CH-OH group of donors, NAD or NADP as acceptor
Biological process: 2-oxoglutarate metabolic process; isocitrate metabolic process; tricarboxylic acid cycle; female gonad development; NADPH regeneration; response to steroid hormone
Cellular component: cytoplasm; cytosol; extracellular exosome; peroxisome; extracellular region; ficolin-1-rich granule lumen; mitochondrion; peroxisomal matrix; secretory granule lumen; tertiary granule lumen
Genetic constraint (gnomAD): Loss-of-function variants: 23 observed, 39.33 expected, observed/expected ratio (o/e) 0.58, 90% interval 0.42 to 0.83. The upper end of that interval is the gene's LOEUF score, 0.83, which puts it in group 3 of 6, group 1 being the genes least tolerant of losing a copy. Missense variants: 378 observed, 488.17 expected, observed/expected ratio (o/e) 0.77, 90% interval 0.71 to 0.84. Synonymous variants: 134 observed, 164.94 expected, observed/expected ratio (o/e) 0.81, 90% interval 0.7 to 0.94.
Homologues: Orthologues: chimpanzee IDH1 (99% identical), macaque IDH1 (99% identical), rabbit IDH1 (98% identical), guinea pig IDH1 (97% identical), dog IDH1 (97% identical), rat Idh1 (96% identical), mouse Idh1 (96% identical), pig IDH1 (96% identical), tropical clawed frog idh1 (88% identical), zebrafish idh1 (83% identical), Caenorhabditis elegans idh-1 (75% identical), Drosophila melanogaster Idh (72% identical). Paralogues in human: IDH2 (69% identical).
Diseases named in the same sentence as IDH1 in open-access papers:
IDH1 is named in the same sentence as 331 diseases in open-access papers, as found by Europe PMC text mining. Sharing a sentence is not in itself a finding about the gene and the disease. The quoted sentences say what the papers report.
glioma (2,478 papers, 2009 to 2026). A benign or malignant brain and spinal cord tumor that arises from glial cells (astrocytes, oligodendrocytes, ependymal cells). "For both classification systems, the IDH1 gene mutation was the most influential feature in predicting glioma grade." (PMID 41596318, 2026). "Gain-of-function mutations in isocitrate dehydrogenase 1/2 (IDH1/2) are frequent in a subset of gliomas and are associated with improved survival compared with wild-type tumors." (PMID 41749891, 2026). "According to the WHO 2021 classification, adult high-grade gliomas are defined by their molecular characteristics, with the IDH1/2 mutation status being the key determinant." (PMID 41596318, 2026). "The goal of this study is to explore the potential for quantitative T imaging to serve as a non‐invasive biomarker for IDH1 gene mutation status in glioma." (PMID 41436375, 2026). "This study is a first exploration of the degree to which IDH-1 mutated glioma subtypes can show different cognitive outcomes." (PMID 41514682, 2026). "Consensus clustering revealed three main glioma groups, which were characterized by distinct survival outcomes, patient age, and IDH1 mutation frequency." (PMID 41596318, 2026). "Though further investigations with larger sample sizes are required to better characterise and understand these findings, ΔT demonstrates potential to serve as a non‐invasive biomarker for IDH1 mutation status in glioma." (PMID 41436375, 2026). "These genes can have mutations which affect glioma growth and grading, with IDH1 mutations being more commonplace than IDH2 mutations." (PMID 41436375, 2026). "In this study, we investigated the potential enhancement of radiation-induced damage of a novel boron-conjugated, ATP-competitive SRC kinase inhibitor, in the U-87 MG glioma cell line and its isogenic cell line stably expressing the IDH1 R132H mutation." (PMID 41901237, 2026). "Similar effects are seen due to elevated levels of the oncometabolite D-2-hydroxyglutarate in gliomas with activating variants of the IDH1 and IDH2 genes encoding the isocitrate dehydrogenase enzymes." (PMID 41546701, 2026). "IDH-mutant gliomas most commonly harbor the canonical IDH1 p.R132H mutation, followed by less common mutations involving IDH1 p.R132 or IDH2 p.R172 codons." (PMID 41736408, 2026). "Given the median age at diagnosis of IDH-1 mutated glioma of about 40 to 45 years, it is likely that such cognitively demanding situations occur often and in different settings (e.g., at home, in social settings and at work)." (PMID 41514682, 2026). "In gliomas, the identification of 2-hydroxyglutarate as an oncometabolite produced by mutant IDH1 not only provided a diagnostic marker but also led to the development of FDA-approved IDH-targeted therapies." (PMID 41209586, 2025). "In 38 patients with glioma, mutations in IDH1/2 (n = 4, 10.5%), TERT promoter (n = 15, 39.5%), 1p/19q codeletion (n = 1, 2.6%), and H3-3A (n = 1, 2.6%) were detected." (PMID 41163986, 2025). "In this work, we present an AI‐assisted strategy to identify IDH1 genotypes of glioma by determining the redox‐associated metabolites." (PMID 40171868, 2025). "Gain-of-function mutations in IDH1/2 result in high D-2HG levels and are implicated in gliomas, leukemias, cholangiocarcinomas, and chondrosarcomas." (PMID 40638696, 2025). "Next, we stratified patients according to the IDH1/2 mutation status and found that 55.4% of IDH1/2-mutant gliomas originated in the frontal lobe compared to 20.7% of IDH1/2-wild-type tumors." (PMID 41377022, 2025).
glioma (continued). "For example, it was shown that despite a BRAF-amplified glioma harboring IDH1/2 and ATRX mutations, known for a better prognosis, a reduced survival was observed vs. V600E mutation v-Raf murine sarcoma viral oncogene homolog B1 BRAFv600E." (PMID 40560010, 2025). "In the most recent WHO classification of brain tumours, the presence of IDH1 mutations is used as a diagnostic marker within glioma (such as astrocytoma, IDH mutant and GB, IDH mutant)." (PMID 39565278, 2025). "Our findings underscore the complexity of predicting glioma pathogenesis and treatment responses based solely on IDH1 mutation status." (PMID 41009641, 2025). "CS predominantly harbors R132C mutations in IDH1, whereas gliomas typically exhibit R132H mutations in IDH1, and AML commonly presents R140Q mutations in IDH2." (PMID 40867318, 2025). "The R132H mutation of IDH1 is the most common in gliomas, accounting for approximately 90% of cases." (PMID 41367876, 2025). "For example, in cases where gliomas exhibit ambiguous imaging features, ML models can flag tumors with radiomic signatures highly indicative of IDH1 mutation, prompting radiologists to consider additional molecular testing or closer follow-up." (PMID 40299088, 2025). "Detecting the IDH1 mutation enables the molecular classification of gliomas and plays an essential role in predicting patient survival outcomes." (PMID 40299088, 2025). "For example, isocitrate dehydrogenase 1 (IDH1) mutations in gliomas inhibit interferon regulatory factor 3/7 (IRF3/7) expression, thereby attenuating type I interferon responses." (PMID 41425703, 2025). "Certain genetic mutations such as those in IDH1/2 genes are known to influence diagnosis, prognosis, and treatment response in glioma patients." (PMID 40814428, 2025). "The definition of glioblastoma was revised to differentiate it from grade-4 gliomas harboring IDH1/IDH2 mutations." (PMID 40867254, 2025). "Tumor-specific somatic mutations also contribute to VTE risk, such as ALK rearrangements increasing the risk in nonsmall cell lung cancer and IDH1 mutations decreasing the risk in gliomas." (PMID 39851266, 2025). "The association between PD-L1 expression, glioma grades, and IDH1 (R132H) mutation status was assessed statistically using SPSS software and a Chi-square test." (PMID 39906459, 2025). "The IDH1 mutation has become a standard diagnostic criterion for glioma classification, with numerous studies indicating its role as an independent prognostic factor in glioma patients." (PMID 40944023, 2025). "Concurrently, IDH1 mutations have been observed in multiple tumors, including glioma, AML, and chondrosarcoma, and are associated with the production of an oncometabolite that promotes an abnormal cellular environment for cancer progression." (PMID 41050081, 2025). "Elevated RIPK1 protein levels correlate with IDH1 wild-type status and increased Ki67 expression, aligning with its association with glioma aggressiveness and correspondingly demonstrating the highest HR for reduced OS." (PMID 41429922, 2025). "In CNS tumors, mutant IDH1 defines distinct glioma molecular subtypes, with IDH1 (R132H) mutations being particularly prevalent." (PMID 40654157, 2025). "In glioma, the discovery of recurrent hotspot mutations in IDH1 and IDH2 genes has provided added rationale to investigate the association between altered metabolism and oncogenesis." (PMID 37398280, 2025). "In gliomas harboring IDH1-R132H mutations, cells exhibit increased mitochondrial mass, enhanced oxygen consumption, and preferential utilization of substrates like glutamate and pyruvate for ATP production." (PMID 40724998, 2025).
glioma (continued). "When comparing IDH1 R132Q glioma xenografts with WT, pathways associated with cell adhesion, integrin binding, and stress response were highlighted as hypermethylated." (PMID 40188944, 2025). "Results of the vaccine trials will be of great interest also for other IDH1 mutated tumors, although in CS, at difference with glioma, the prevalent IDH1 mutation is R132C." (PMID 40004005, 2025). "In any case, the glioma therapeutic landscape has seen significant advances with the approval of vorasidenib by the FDA in August 2024 for grade 2 gliomas with IDH1/IDH2 mutations." (PMID 40864821, 2025). "Understanding the interplay between PD-L1 expression, IDH1 (R132H) mutations, and the tumor microenvironment is essential for advancing glioma treatment." (PMID 39906459, 2025). "The human glioma samples that metabolically resembled fly tumors harbored a significantly lower number of mutations and showed strong enrichment for IDH1 mutations, and the patients in the similar group had better survival outcome." (PMID 40523311, 2025). "Our experimental results suggest that the study can effectively improve the utilization of glioma imaging data and the accuracy of intelligent diagnosis of glioma IDH1 mutation status." (PMID 40323991, 2025). "In patients with IDH1-mutated gliomas, the expression levels of tissue factor (TF) and podoplanin (PDPN) are lower, and high expression of these proteins is associated with increased VTE risk." (PMID 40873733, 2025). "In gliomas, IDH1 mutations disrupt chromosomal neighborhoods through CTCF hypermethylation, while YY1 mediates chromatin loops and transcription elongation." (PMID 40565099, 2025). "We subsequently surveyed 3 molecular signatures with positive prognostic significance across different age groups in glioma: IDH1/2-mutation, MGMT-methylation, and 1p19q codeletion." (PMID 39164213, 2025). "Our study demonstrated that the LR model based on multivariable combined parameters showed good diagnostic performance in estimating IDH1 mutation in gliomas." (PMID 40134593, 2025). "Despite this challenge, a trend unique to IDH1 R132Q emerged in both chondrosarcoma and glioma xenografts – hypermethylation of pathways associated with DNA damage." (PMID 40188944, 2025). "One study investigated the presence of 20 common glioma mutations, including IDH1, IDH2, and ATRX, within the analyzed pituitary tumours, of which 1/248 tumours exhibited a loss of ATRX due to a large deletion within the gene." (PMID 40440300, 2025). "Mutations in the IDH1 gene have been associated with numerous malignancies including lower-grade gliomas as the mutant IDH1 enzyme catalyzes the conversion of α-KG to D-2-hydroxyglutarate (D-2HG), an oncometabolite." (PMID 40507361, 2025). "For instance, IDH-mutated gliomas exhibit selective responses to the IDH1/2 dual-target inhibitor Vorasidenib, while leukemia patients carrying KMT2A rearrangements or NPM1 mutations." (PMID 41335282, 2025). "Further subgroup analysis by IDH-1 mutation status showed that IDH-1-wildtype gliomas had significantly higher abnormality index values than IDH-1-mutant tumors (t = 3.17, p = 0.003), independent of tumor volume (ANCOVA, p = 0.005)." (PMID 40647472, 2025). "Currently, there is a lack of studies investigating the association between SWE and SMI features and IDH1 mutation status in gliomas." (PMID 40944023, 2025). "Frontal lobe gliomas harbored IDH1/2 mutation in 63.5% of cases compared to 36.5% of cases with IDH1/2-wild-type tumors." (PMID 41377022, 2025). "In IDH1/2-wild-type gliomas, high frequencies of TERTp mutations (48.9%), EGFR amplifications (29.7%), PTEN alterations (27.9%), and chromosomal 7+/10− alterations (27.5%) correlated with advanced age and poor prognosis." (PMID 41377022, 2025).
glioma (continued). "Regarding molecular markers, IDH1 mutations were present in 55 patients (50.9%), whereas 53 patients (49.1%) had IDH1-wildtype gliomas." (PMID 40299088, 2025). "A total of 152 glioma patient data with confirmed IDH1 mutation status were retrospectively collected." (PMID 40134593, 2025). "IDH1/2 mutant gliomas—particularly those with more favorable histologic features—are associated with a greater survival than IDH1/2 wildtype GBM which is characterized by a median survival of approximately 15 months." (PMID 41301687, 2025). "This study uncovers candidate biomarkers and pathways relevant to glioma progression and therapeutic targeting, but also underscores the complexity of predicting glioma pathogenesis and treatment responses based on IDH1 mutation status." (PMID 41009641, 2025). "IDH1 mutations are commonly found in lower-grade gliomas (WHO grades II and III) and secondary glioblastomas." (PMID 40075667, 2025). "DRG2 was previously shown to be downregulated in IDH1-mutant gliomas, where ATRX mutations are common." (PMID 40775769, 2025). "In the classification of glioma IDH1 mutation status, an average accuracy rate of 94.35% was obtained." (PMID 40127071, 2025). "This study builds on previous research by examining the immune landscape in gliomas and examining the relationship among IDH1 (R132H) mutations, glioma grades, and PD-L1 expression." (PMID 39906459, 2025). "IDH1 wild-type gliomas exhibited higher blood perfusion, and MRI sensitivity for diagnosing IDH1 mutations ranged between approximately 75.0% and 85.0%." (PMID 40944023, 2025). "Circulating cell-free DNA (cfDNA) can be used in liquid biopsies to detect IDH1 mutations in glioma patients (especially IDH1-R132H)." (PMID 40564017, 2025). "The paucity of evidence linking D2hgdh mutations with glioma occurrence is striking considering the wide-spread prevalence of IDH1/IDH2 mutations in these tumors." (PMID 40236175, 2025). "Ivosidenib (AG-120), for example, has shown promising clinical antitumor activity in glioma patients with IDH1 mutations, and it has been well tolerated by patients, though the optimal dosing for glioma treatment is still under investigation (NCT02073994)." (PMID 40113789, 2025). "Genera such as Capnocytophaga and Leptotrichia were more prevalent in low-grade gliomas and IDH1-mutant tumours, indicating possible diagnostic or prognostic value." (PMID 41516317, 2025). "Isocitrate dehydrogenase 1 (IDH1) mutations are key drivers of glioma biology, influencing tumor aggressiveness and treatment response." (PMID 41009641, 2025). "Taken together, these findings suggest a link between IDH1 mutation and the upregulation of autophagy-related pathways in glioma." (PMID 40964044, 2025). "In conclusion, this study identified multifocal lesions, larger tumor size, and higher WHO grade as independent adverse prognostic factors in glioma, while chemotherapy, IDH1/2 mutations, and MGMT promoter methylation were associated with improved survival." (PMID 41398783, 2025). "As a biomarker related to the malignancy of gliomas, IDH1 mutation took up 65% of the general in Cluster 1, higher than that of Cluster 2, 54%." (PMID 41425851, 2025). "Mutations in the isocitrate dehydrogenase (IDH1/2) are highly frequent genetic abnormalities in human cancerous diseases such as glioma, leukemia, chondrosarcoma, and cholangiocarcinoma." (PMID 39920158, 2025).